SNORD113-9 (small nucleolar RNA, C/D box 113-9)
Synonyms: 14q(I-9)
Gene: Small nucleolar RNA gene on chromosome 14 (100,945,649 to 100,945,720, forward strand). Ensembl gene ENSG00000201950.
Gene Ontology:
Biological process: RNA processing
Cellular component: nucleolus
Homologues: Orthologues: chimpanzee SNORD113-9 (100% identical), macaque SNORD113-9 (97% identical), guinea pig SNORD113-9 (94% identical), pig SNORD113-9 (90% identical), rabbit SNORD113-9 (86% identical), mouse Gm55110 (85% identical). Paralogues in human: SNORD113-3 (89% identical), SNORD113-4 (82% identical), SNORD113-8 (79% identical), SNORD113-7 (78% identical), SNORD113-5 (76% identical), SNORD113-6 (76% identical), SNORD114-12 (72% identical), SNORD113-1 (71% identical), SNORD114-14 (71% identical), SNORD114-23 (71% identical), SNORD114-9 (71% identical), SNORD114-22 (69% identical), and 26 more.